INS (insulin)
Diseases named in the same sentence as INS in open-access papers (continued):
Sharing a sentence is not in itself a finding about the gene and the disease.
Insulin resistance (continued). "Nevertheless, insulin signaling is impaired in LRP1 NPxY mutant hepatocytes and this mutation does not exacerbate or protect against HFHC diet-induced hyperglycemia, hyperinsulinemia, and insulin resistance." (PMID 33500241, 2021). "For example, the understanding of Cx-mediated transmission of endoplasmic reticulum stress and its relationship with obesity, or the interplay between insulin signaling, insulin resistance, and gap junction function, are topics of scientific interest that need to be investigated in greater depth." (PMID 34830025, 2021). "In addition, insulin resistance and the compensatory increase in plasma insulin levels progressively worsen this hyperandrogenemia, acting on different tissues." (PMID 34884872, 2021). "Estrogens and their receptors are discussed to play important roles in regulating body weight and insulin sensitivity, although exact mechanisms of estrogen-mediated adaptation of β-cell response to insulin resistance is unknown." (PMID 34884524, 2021). "Insulin resistance occurs when fasting insulin is HOMA-IR>2." (PMID 35310326, 2021). "Here we sought to determine whether 3 months of 4 g/day ω-3PUFA improves insulin sensitivity in subjects with obesity and documented evidence of insulin resistance and systemic inflammation." (PMID 33753887, 2021). "Thus, MCTs participated in insulin resistance by reducing insulin's binding affinity to its receptor." (PMID 34257700, 2021). "Additionally, the extent of Netrin-1 was found to be inversely related to the homeostasis model evaluation of insulin resistance and plasma glucose (fasting and post-meal), fasting insulin, triglyceride, and hemoglobin A1c levels." (PMID 34179515, 2021). "Before and after the intervention, fasting blood sugar (FBS), serum glycosylated hemoglobin (HbA1c), serum insulin, the homeostasis assessment model for insulin resistance (HOMA-IR), body mass index (BMI), and systolic and diastolic blood pressure were determined and compared between the two groups." (PMID 34285701, 2021). "The methylation of the PPARG promoter was higher by about two times after 48 h (p = 0.006) and three times after 72 h (p = 0.024) of insulin resistance induction compared to adipocytes with proper insulin sensitivity; this correlated with the expression of this gene in experimental adipocytes." (PMID 34207541, 2021). "Our results suggest that reductions in LRRC8A signaling may contribute to impaired vascular function observed in humans in response to insulin and/or shear stress in the setting of obesity and insulin resistance." (PMID 33629656, 2021). "The ethnic differences among NAFLD patients could probably be explained by an increased insulin resistance where Asian Indians were reported to have the least insulin sensitivity compared to Chinese or Malay males." (PMID 34307250, 2021). "Although traditional references suggest a cut-off of 100 μU/mL as grading severe insulin resistance, a few studies questioned whether ethnicity, race may affect insulin sensitivity and end organ response." (PMID 33782517, 2021). "In addition, women with NGT 1h high exhibited an impaired insulin secretion and greater insulin resistance already during pregnancy than NGT women with 1h-OGTT low." (PMID 34108933, 2021). "Elevated levels of palmitate, stearate, and S1P have been shown to be instrumental in inducing insulin resistance, suggesting that an altered neuronal lipid and fatty acid metabolism might impact insulin action and energy metabolism." (PMID 33946318, 2021). "While an association between long-chain fatty acids and insulin sensitivity in obese, insulin resistant patients has been shown that does not seem to apply during the early onset of insulin resistance in our model." (PMID 34727112, 2021).
Insulin resistance (continued). "Although there were no significant changes in blood glucose levels in HIF1αKOMBH mice, the serum insulin levels of HIF1αKOMBH mice were significantly increased, suggesting that mice with neuronal HIF1α knockout in the mediobasal hypothalamus developed insulin resistance." (PMID 34733235, 2021). "We hypothesized that the combined intervention group would lead to the greatest decrease, compared to control, in adiposity and concomitant beneficial changes in insulin, C-peptide, and insulin resistance." (PMID 34578984, 2021). "Indeed, the serum level of insulin, C-peptide and homeostasis model assessment for insulin resistance (HOMA-IR) were significantly higher in patients with alopecia areata compared to controls." (PMID 34226603, 2021). "Physical exercise, in turn, moderates the inflammatory condition, decreasing the secretion of leptin and TNF-α, which is a metabolic cascade of changes in other adipokines, it reduces the secretion and cytokines of the insulin antagonist and subsequently improves insulin resistance." (PMID 34568974, 2021). "Insulin resistance, the blood insulin level should be normal or elevated." (PMID 34671214, 2021). "Similarly, the elevated levels of free fatty acids, insulin, and glucose, observed in insulin resistance, induce macrophages activation." (PMID 34829598, 2021). "However, in some of the included studies that did not measure HbA1c levels, other positive changes in systemic parameters such as interleukin (IL)-6 levels, high-sensitive C-reactive protein levels, insulin, and insulin resistance were obtained." (PMID 34439554, 2021). "Leptin, also, affects the insulin sensitivity, inducing insulin resistance and lipid accumulation." (PMID 33584134, 2021). "This is suggested as an additional factor for insulin resistance and impaired insulin secretion." (PMID 33320449, 2021). "Notably, intraperitoneal glucose and insulin tolerance tests demonstrated that adipo-rac1-KO mice developed whole-body glucose intolerance and insulin resistance." (PMID 34639094, 2021). "Furthermore, vitamin D deficiency reduces calcium level in peripheral tissues leading to a reduction in insulin secretion from the beta cells of pancreatic and subsequently increases insulin resistance in obese patients." (PMID 34505755, 2021). "Insulin resistance at the level of fatty tissues leads to reduced insulin-mediated glucose uptake for conversion into fats, and increased lipid breakdown, with an elevation of the free fatty acids (FFAs) and cytokines, leading to a state of chronic inflammation." (PMID 34712528, 2021). "The pathogenesis of T2DM is still not completely clarified but could be simply come down to two aspects: dysfunction of insulin secretion capacity and peripheral insulin resistance." (PMID 33728329, 2021). "Besides lifestyle modification, metformin is commonly used as an insulin sensitive agent that reduces fasting glucose, improving insulin resistance in patients with PCOS." (PMID 33669954, 2021). "We also demonstrated a significant reduction in insulin‐stimulated glucose transport in cells depleted of BCKD, especially in myotubes incubated with KIC, consistent with the assertion that defects in muscle BCAA catabolism is causative for insulin resistance." (PMID 33400857, 2021). "The major cause for diet-induced obesity and insulin resistance is the overactivation of mTOR that down-regulates insulin signaling via negative feedback regulation through the phosphorylation of IRS1 at serine residues." (PMID 34445300, 2021). "Enhanced insulin resistance could result in lower insulin efficiency, and inhibit glucose uptake and utilization." (PMID 34185184, 2021). "GCs are potent inducers of insulin resistance in all insulin-sensitive tissues." (PMID 33435513, 2021). "On the other hand, anti-hypertensive drugs were shown to enhance insulin sensitivity, implying that improving the cardiovascular system might exert beneficial effects on insulin resistance." (PMID 33968046, 2021).
Insulin resistance (continued). "Moreover, Crtc1–/– mice were more prone to insulin resistance and dyslipidemia, as evidenced by higher levels of plasma glucose, insulin and FABP4 than wildtype mice." (PMID 33912553, 2021). "The higher levels of insulin we found in subjects exposed to only CT and to both CT and SLEs seem to suggest that CT may act as a “first hit” with the appearance of insulin-resistance, which later can, in turn, bring a rise in insulin levels." (PMID 34054596, 2021). "This may be partially explained by sex differences,sucrose‐induced insulin‐resistant models have only been successfully created in male animals, and females appear to be resistant to sucrose‐induced insulin resistance." (PMID 33532625, 2021). "To check whether the insulin resistance phenotype was accompanied by insulin secretion defects, we performed an in vivo GSIS experiment." (PMID 35111136, 2021). "CE improves insulin resistance through the enhancement of insulin action." (PMID 34627352, 2021). "These previous studies suggested that the gut microbiota may be responsible for the recovery of the tight junctions in the intestine and the insulin signaling pathway to improve liver steatosis and insulin resistance in NAFLD." (PMID 33708180, 2021). "Thus, although there is strong evidence for ceramides to be involved in insulin resistance, further research is needed to elucidate the mechanisms for each species and its impact on insulin-resistant states." (PMID 33923531, 2021). "Altered gene expression in specific organs may be reflected in whole blood; hence, we think that our results may reflect obesity and/or insulin resistance-related organ dysfunction in the insulin-resistant individuals." (PMID 34886800, 2021). "Serum insulin levels were significantly reduced, insulin resistance decreased, and insulin sensitivity increased, which indicated that sericin could enhance the effects of insulin on glucose absorption and utilization." (PMID 34439921, 2021). "In addition, insulin resistance appears as a consequence of the inability of insulin to induce the appropriate effect on glucose metabolism." (PMID 34440963, 2021). "Another Japanese study suggested that insulin, C-peptide and homeostasis model assessment of insulin resistance (HOMA-IR) but not glucose level were associated with an increased risk of GCa." (PMID 34356646, 2021). "Interestingly, the GLP-1 receptor knock-out mice were also protected from insulin resistance (specifically hepatic insulin activity) when placed on a high-fat diet." (PMID 35010994, 2021). "Low-grade systemic inflammation is one of the earliest and main pathological events that might lead to the development of insulin resistance in most insulin-sensitive tissues." (PMID 33967682, 2021). "Insulin resistance (IR) in skeletal muscle has been attributed to different pathological conditions such as mitochondrial dysfunction, impaired glycogen synthesis, and accumulation of diacylglycerol with subsequent impairment of insulin signaling." (PMID 33639916, 2021). "Insulin is a critical negative regulator of synovial inflammation and catabolism; thus, development of insulin resistance in an obese population would diminish the ability of insulin to suppress production of inflammatory and catabolic mediators that promote OA." (PMID 33668426, 2021). "Since IL-6 may regulate peripheral insulin resistance, it was hypothesized that blockade of the IL-6 pathway with tocilizumab would result in improved insulin sensitivity." (PMID 34747368, 2021). "A high level of hemoglobin can lead to decreased blood flow by increasing blood viscosity and subsequently reduce the delivery of oxygen, glucose and insulin to essential tissues, which might induce insulin resistance." (PMID 33740939, 2021). "Together these findings support that PDH regulates insulin sensitivity in human skeletal muscle and therefore may function as a therapeutic target for the treatment of skeletal muscle insulin resistance." (PMID 34042297, 2021).
Insulin resistance (continued). "One small cross-sectional study concluded that increased steatosis of the liver is associated with lower insulin clearance, which contributes to insulin resistance in non-diabetic subjects." (PMID 33921359, 2021). "Insulin resistance (IR) is characterized as a condition in which sensitivity to insulin and its downstream signaling pathways is decreased in three primary insulin sensitive metabolic tissues– skeletal muscle, liver, and white adipose under normal serum glucose concentrations." (PMID 33820928, 2021). "Insulin resistance is a condition of reduced responsiveness to insulin." (PMID 33801684, 2021). "In severe metabolic disorders associated with insulin resistance, insulin fails to suppress gluconeogenesis in the liver while the induction of hepatic lipogenesis is sustained, eventually leading to both hyperglycemia and hyperlipidemia." (PMID 34676828, 2021). "Hepatic insulin resistance, defined as increased post absorptive glucose synthesis and decreased sensitivity to insulin-mediated inhibition of endogenous glucose production, is only seen in obese women with PCOS when compared to healthy women of equivalent body weight." (PMID 34745009, 2021). "Moreover, we propose that pioglitazone alleviates HFCD-mediated insulin resistance by stabilizing anti-oxidative and anti-inflammatory factors, and improving insulin sensitivity." (PMID 34037093, 2021). "The chronic exposure to immunosuppressive agents represents a unique risk factor to kidney transplant recipients, attributed to the toxic or inhibitory (possibly reversible) effects of these drugs to pancreatic islet beta cells and manifesting as insulin resistance or impaired insulin secretion." (PMID 36994340, 2021). "Notably, OGT can participate in insulin resistance as a number of insulin signaling intermediates undergo O-GlcNAcylation." (PMID 33925229, 2021). "The integrated physiology of insulin resistance owes to defective insulin action at target cells." (PMID 34071721, 2021). "In particular, the accumulation of muscle DAGs in the present study may have further implications for metabolic regulation through insulin signaling, as muscle DAG accumulation has been linked to induction of insulin resistance via protein kinase C." (PMID 33667994, 2021). "They thought that hypokalemia may decrease insulin secretion and induce insulin resistance, followed by dysbiosis of glucose metabolism." (PMID 34484110, 2021). "Interestingly, several derivatives of inositol have been classified as insulin-sensitizers and seem to counteract insulin resistance-related metabolic diseases with a safe nutraceutical profile." (PMID 34684668, 2021). "Studies have suggested that dietary insulin load and FII could be considered as independent dietary risk factors for the development of insulin resistance that contributes to its pathogenesis NAFLD." (PMID 34221261, 2021). "We consider that aging could induce insulin resistance through abnormal-insulin-signaling-related genes, and ultimately lead to glucose intolerance and kidney dysfunction." (PMID 33795778, 2021). "Cluster 2 included elderly patients with optimal vitamin D status, good glycemic control (the lowest levels of eAG and HbA1c), low insulin resistance (the lowest levels of insulin, HOMA-IR, and TYG index), the highest mean level of HDL, and lowest mean levels of TG and BMI." (PMID 34239695, 2021). "The insulin-dependent IRS2-AKT signaling pathway is the main pathway of insulin resistance." (PMID 34485269, 2021). "This review examines epidemiologic research on circulating biomarkers of thyroid function (hormones, thyroid autoantibodies), glucose metabolism (blood glucose, glucose tolerance), and insulin secretion (insulin resistance) to offer mechanistic insight into subclinical and clinical GDM." (PMID 34022907, 2021).
Insulin resistance (continued). "Our results demonstrated that 8-week TCDD exposure could induce insulin resistance in rats, while exercise could improve insulin sensitivity in which moderate intensity was more obvious than high intensity exercise." (PMID 34948750, 2021). "Adipocyte dysfunction can contribute to insulin resistance and impaired insulin secretion." (PMID 34943836, 2021). "Therefore, ceramide is now widely accepted as a potent insulin antagonist involved in the pathophysiology of insulin resistance and DM, especially in overweight and obese people." (PMID 34660812, 2021). "Hence, it is evident that vitamin D affects glucose homeostasis through reduced insulin secretion, increased insulin resistance and hyperglycemia." (PMID 33801988, 2021). "Indeed, studies have highlighted that long-chain acylcarnitines interfere with muscle insulin signaling at the level of AKT phosphorylation and are associated with muscle insulin resistance." (PMID 34959870, 2021). "In addition, changes in sleep patterns lead to lower glycemic control, as they infer a greater need for daily insulin in patients with increased social jet lag, due to increased insulin resistance and lower glycemic monitoring." (PMID 34614139, 2021). "Thus, in mice, hepatocyte-specific overexpression of DPP4 is associated with hepatic insulin resistance and liver steatosis, whereas knockdown of DPP4 improves insulin sensitivity and reduces lipid accumulation in cultured hepatocytes." (PMID 33691757, 2021). "In previous studies, it have been outlined that AGEs could lead to insulin resistance in adipocytes through impede insulin-mediated glucose transport and uptake." (PMID 34122100, 2021). "In addition, the administration of icv-STZ triggers insulin resistance and then impairs insulin signaling in the brain, but the peripheral glucose level was not changed in 3 × Tg-AD mice, as shown in previous study." (PMID 34627204, 2021). "Additionally, separating the impact of insulin compared to other factors involved in insulin resistance (i.e., high glucose) is difficult to parse out." (PMID 34829566, 2021). "This is a typical symptom seen in insulin-resistant animal models and diabetic patients, and may be useful as a model for drug testing and drug discovery of insulin resistance." (PMID 34358068, 2021). "However, insulin secretion is insufficient for patients with higher glucose levels to compensate with insulin resistance." (PMID 33435282, 2021). "Additionally, sevoflurane anesthesia has been shown to increase plasma glucose levels by impairing insulin secretion, inducing insulin resistance, and reducing glucose uptake and utilization." (PMID 34555043, 2021). "It is clear that increased oxidative stress may lead to insulin resistance and impose an impact on insulin secretion in patients having depressive disorder." (PMID 34912246, 2021). "Brain insulin resistance is shown to a disturbance of brain insulin signaling in experimental animals, which is represented by the attenuation of insulin receptor substrate-2 (IRS2) → phosphoinositide 3-kinase → phosphorylated Akt → phosphorylated glycogen synthase kinase-3β (GSK-3β)." (PMID 33494481, 2021). "Insulin resistance is defined as reduced tissue responsiveness to the action of insulin." (PMID 33597002, 2021). "Furthermore, the data indicates that pFet A, but not total Fet A is associated with BMI, waste circumference, total body fat, serum glucose, serum insulin, and insulin resistance." (PMID 33499061, 2021). "Thus, markers associated with insulin resistance (high BCAA, glutamate and C3/C5 and low urea cycle AA) at baseline predicted increases in metrics of insulin sensitivity (decreased TG/HDL and increased adiponectin) during lifestyle intervention." (PMID 34277974, 2021).